SOX4 (SRY-box transcription factor 4)
Diseases named in the same sentence as SOX4 in open-access papers (continued):
Sharing a sentence is not in itself a finding about the gene and the disease.
melanoma (37 papers, 2011 to 2025). A malignant, usually aggressive tumor composed of atypical, neoplastic melanocytes. "Collectively, these data provide strong evidence establishing SOX4 as a potential melanoma risk gene." (PMID 39802764, 2024). "We validated several such cis-regulatory interactions using CRISPR inhibition, providing evidence for known cancer driver genes MDM4 and CBL, as well as the SRY-box transcription factor SOX4, as likely melanoma risk genes." (PMID 39802764, 2024). "Relevant to the current study is a previous report that loss of Sox4 promotes melanoma cell invasion via a mechanism that involves activation of NFκB." (PMID 30683134, 2019). "Our previous studies found that 12 markers including pAkt, Bim, BRG1, BRMS1, CTHRC1, Cul1, ING4, MCL1, NQO1, SKP2, SNF5 and SOX4 were associated with melanoma progression." (PMID 23028750, 2012). "Recent reports indicate that SOX4 promotes tumor proliferation by regulating glycolysis through activation of AKT in melanoma cells, yet the role of SOX4 in carbohydrate metabolism reprogramming to regulate cell plasticity is still poorly understood." (PMID 39014441, 2024). "In addition, all three of these variants are marginal eQTLs for SOX4 in TCGA melanomas (rs6935117, P = 0.01; rs6935124, P = 0.01; and rs2125570, P = 0.01) with direction of effect matching reporter assay data, i.e. risk alleles for these variants are associated with higher SOX4." (PMID 39802764, 2024). "MSC-derived EVs was demonstrated to induce the apoptosis of melanoma cells via transmitting miR-138-5p, and then targeted SOX4." (PMID 37575250, 2023). "Authors found that elevated miR-138-5p levels in EVs reflected increased cell apoptosis, restraining melanoma progression; this effect was directly driven by SOX4, a stemness marker targeted by miR-138-5p." (PMID 37239847, 2023). "An aberrant expression of SOX4 is present in different cancer types, including melanoma, which promotes cell migration and invasion." (PMID 37375678, 2023). "One study reported that miR-129 acts as a tumor suppressor, and its overexpression leads to decreased cell proliferation and viability of melanoma cells resistant to vemurafenib, possibly by modulating SOX4 expression." (PMID 37047539, 2023). "The SOX4 transcription factor is reported to be upregulated in melanoma believed to be involved in metabolic rewiring." (PMID 35269844, 2022). "The ubiquitous expression in melanoma metastases suggests a general role of SOX4 for cell maintenance in vivo and in vitro." (PMID 36435874, 2022). "In the Oncomine database, SOX4 expression was upregulated in most types of cancer except melanoma and ovarian cancer." (PMID 34442467, 2021). "SOX4 seemed a likely fitting candidate, since it is not only induced during melanoma progression and promotes melanoma proliferation by AKT signaling activation, but also mediates to BRAFi in melanoma through regulation of IGF-1R." (PMID 34063443, 2021). "The results of our study demonstrate that EZH2 dependent repression of miR-129-5p is solved by BRAFi/MEKi treatment thereby modulating BRAFi resistance and melanoma progression via targeting SOX4." (PMID 34063443, 2021). "For example, miR-140-5p directly targeted SOX4 to participate in tumorigenesis in malignant melanoma." (PMID 34258391, 2021). "In Western blot analyses, we determined a decreased SOX4 protein level in miR-129-5p overexpressing melanoma cell lines." (PMID 34063443, 2021). "These genes included SKP2, TOP2A, SOX4, MAP2 and CTLA4, all of which have been associated with patient outcome in melanoma." (PMID 29193607, 2018). "Immunohistochemical expressions of 12 promising biomarkers (pAkt, Bim, BRG1, BRMS1, CTHRC1, Cul1, ING4, MCL1, NQO1, SKP2, SNF5 and SOX4) were studied in 122 melanomas and 33 dysplastic nevi on tissue microarrays." (PMID 23028750, 2012).
melanoma (continued). "The SOX4 level is elevated in numerous human cancers, including of the bladder, prostate, endometrium, and liver, whereas it is decreased in melanoma and gallbladder cancer." (PMID 23285187, 2012). "SOX4 downregulation was correlated with a poor prognosis and SOX4-depleted melanoma cells showed enhanced invasion and migration." (PMID 21647268, 2011). "Among the genes found to be downregulated in the UVM subtracted library, several were previously associated with melanoma, such as melanocytic markers TYRP1, EDNRB, MTAP, and sex determining region Y box 4 (SOX4)." (PMID 21647268, 2011). "LncMEG3 could also affect SOX4-mediated malignant proliferation of melanoma cells through the regulation of miR-208 and inhibit melanoma development." (PMID 38271137, 2024). "Moreover, it was reported that miR-129-5p binded with the SOX4 gene, which induced BRAFi sensitivity in melanoma cells." (PMID 36982460, 2023). "The authors have speculated that EZH2 is responsible for the regulation of miR-129-5p/SOX4 axis, since EZH2-specific methyltransferase inhibitor tazemetostat triggered miR-129-5p diminution and reactivation of SOX4 in drug-resistant melanoma cell lines." (PMID 37325482, 2023). "In conclusion, the upregulation of miR-129-5p, as well as the blocking of SOX4, could be used to ensure better treatment outcomes in melanoma BRAFi-resistant cells." (PMID 36982460, 2023). "In addition, miR-129-5p suppressed proliferation and invasion of chondrosarcoma cells via targeting SOX4/Wnt/β-Catenin pathway and miR-140-5p targeted SOX4 to retard tumorigenesis and progression in malignant melanoma by blocking the Wnt/β-Catenin pathway." (PMID 35241028, 2022). "SOX4 expression could control the Wnt/β-catenin pathway in many cancers, such as melanoma and endometrial cancer." (PMID 35241028, 2022). "In addition, it has been reported that SOX4 can promote the migration and invasion of melanoma cells by activating the NF-κB pathway." (PMID 35573654, 2022). "A previous study indicated that SOX4 could promote melanoma cell migration and invasion by activating the NF-κB pathway." (PMID 35573654, 2022). "Finally, we found that miR-129-5p decreases melanoma cell proliferation and improves response to BRAFi by targeting SOX4." (PMID 34063443, 2021). "Taken together our results emphasize SOX4 as a potential therapeutic target in BRAF driven melanoma which could be attacked by pharmaceutically, e.g., by miR-129-5p mimics." (PMID 34063443, 2021). "Recent reports indicate that decreased Sox4 expression promotes invasion in melanoma." (PMID 30683134, 2019). "In addition, SOX4 expression was reduced in metastatic malignant melanoma compared with dysplastic nevi and primary melanoma." (PMID 21647268, 2011). "SOX4 regulates melanoma glycolytic metabolism controlling the transcriptional expression of glucose transporter type 1, hexokinase 2, and lactate dehydrogenase A, and activates mTORC1 to promote proliferative signals and cell growth when SOX4 is upregulated by CD147." (PMID 36661515, 2023). "Thus, modulation of the miR-129-5p-SOX4 axis could serve as a promising novel strategy to improve response to BRAFi in melanoma." (PMID 34063443, 2021). "Within the SOX gene family, SOX4, SOX5, SOX9 and SOX10 are established key regulators in melanoma cells establishment and function." (PMID 40866912, 2025). "It is of note that the in vitro stable IFN resistance 11-core DEGs contained two melanoma oncogenes, SOX4 and DEK (transcription factors); the former was reported to be downregulated, while the latter was found to be upregulated during melanoma progression." (PMID 35269844, 2022). "Taken together our results emphasize miR-129-5p, as well as SOX4, as potential therapeutic targets in BRAF-driven melanoma." (PMID 34063443, 2021). "One potential target of miR-129-5p is SOX4, which was reported to induce cell proliferation and to mediate BRAF inhibitor resistance in melanoma." (PMID 34063443, 2021).
melanoma (continued). "Intriguingly, analysis of a zebrafish model found SOX4 to be a marker of stress-like cell population that more efficiently seeded new tumors; induction of a stress-like program conferred resistance to both BRAF and MEK inhibition in zebrafish melanoma cells." (PMID 39802764, 2024). "Our in silico analysis of IFN-treated melanoma tissues of TCGA revealed the differential expression of five members of our 79 IFN-res DEGs in IFN-treated melanoma tissues: IRG SOX4 and non-IRGs WFDC1, BCAN, RPE65, and MAPT." (PMID 35269844, 2022). "From this perspective, it is of note that the IFN therapy and the ICI therapy predictive genes of our IFN resistance DEGs overlapped by three genes, WFDC1, SOX4, and BCAN, strongly suggesting a connection between the two pheno-/geno-types of melanoma: IFN and ICI resistance." (PMID 35269844, 2022). "When the predictive power of all of these genes was tested on an ICI-treated melanoma patient cohort, 11 out of the 13 in vitro stable (containing IRGs SOX4, DEK, and HSPA1B) and AQP1 and CDCA4 in vivo stable DEGs were differentially expressed in the tumors of ICI responder melanoma patients." (PMID 35269844, 2022). "Besides, SOX4 is also involved in the promotion of amino acid and glycerophospholipid metabolism in acute myeloid leukemia, and regulation of glycolysis through activation of the AKT pathway in melanoma cells." (PMID 39014441, 2024).
glioma (36 papers, 2010 to 2025). A benign or malignant brain and spinal cord tumor that arises from glial cells (astrocytes, oligodendrocytes, ependymal cells). "This temporal ordering indicated that the C3 SOX4+ glioma subpopulation is associated with early tumorigenesis, differentiating into other subpopulations as tumor progression occurs." (PMID 40630954, 2025). "We additionally analyzed the expression of a panel genes (Angpt2, Sox4, Vegfa, Kdr, Itga1, Mcam, Notch4 and Ets1) associated with vascular abnormality in ECs using RNA extracted from total glioma tumor tissues from control and treated mice." (PMID 34867089, 2021). "SOX4 was implicated in the promotion of self‐renewal and stemness in gliomas." (PMID 36987665, 2023). "Similar role of miR-204 has been also proved in gliomas, where low miR-204 expression leaded to a stem cell-like phenotype, and its overexpression resulted in reduced tumorigenicity and loss of stemness transcription factor SOX4." (PMID 26126974, 2015). "Importantly, loss of miR-204 has been associated with a stem cell-like phenotype in gliomas, and its over-expression results in reduced tumorigenicity and loss of the stemness transcription factor, SOX4." (PMID 24025188, 2013). "In the past, it has been indicated that SOX4 has a suppressive effect on the cell growth of glioma stem cells." (PMID 35686099, 2022). "HNF1A‐AS1 exerted oncogenic property in glioma progression via upregulating miR‐32‐5p–mediated SOX4 expression, suggesting potential novel therapeutic target for future glioma treatment." (PMID 33448691, 2020). "Together, these results confirmed the ceRNA role of HNF1A‐AS1 in glioma via regulating miR‐32‐5p/SOX4 axis." (PMID 33448691, 2020). "In the field of glioma, SOX4 has been found to be significantly elevated in glioblastoma multiforme." (PMID 33448691, 2020). "This expression status is contrary to that of miR‐32‐5p in glioma cells, thus we chose SOX4 to study." (PMID 33448691, 2020). "Herein, we also detected the abnormal upregulation of SOX4 in glioma cells in comparison to normal control cell, which was the same expression profile previously revealed in medulloblastoma." (PMID 33448691, 2020). "Given the ability of miR-204 to target SOX4, it is suggested that altered abundances of SOX4 and EphB2 together are involved in modulating stemness and migration of glioma cells." (PMID 29682554, 2018). "For example, we found SOX2 is upregulated by SOX4, which is consistent with previous findings that the transforming growth factor-β (TGF-β)-Sox4-Sox2 pathway is essential for glioma-initiating cells to retain their stemness." (PMID 25366337, 2014). "In glioma, SOX4 expression is directly induced by TGF-β activated SMAD2/3, resulting in the maintenance of sternness and tumorigenicity." (PMID 23301048, 2013). "The fact that Olig1 and Sox4 mRNA levels were reduced in MNF-treated C6 glioma tumors compared with the control group is consistent with decreased activation of molecular pathways leading to gliomagenesis." (PMID 25505565, 2013). "Taken together with our findings, this study supports the potentially important role of TGF-beta signaling through the SOX4 protein in gliomas." (PMID 20419098, 2010). "Mounting articles exhibited that SOX4 was highly expressed in glioma and glioblastoma tissues." (PMID 36987665, 2023). "For example, it had been found that the growth and migration of chondrosarcoma cells could be restrained by targeting SOX4 and inhibiting glioma cells’ proliferation by targeting TGIF2." (PMID 35456485, 2022). "The role of SOX4 in glioma is controversial insofar as conflicting reports exist on SOX4 activity and expression, suggesting that its function may be context dependent." (PMID 34012965, 2021). "LncRNA X inactive-specific transcript (XIST) promoted metastasis of glioma by miR-133a/SOX4." (PMID 34381023, 2021).
glioma (continued). "Interestingly, we found that a subset of TAMs also express genes encoding the markers of glioma cells, such as GFAP, DLL3, OLIG1 and SOX4." (PMID 34805184, 2021). "To further determine whether HNF1A‐AS1 facilitated glioma via acting as a ceRNA in regulating miR‐32‐5p/SOX4 network, we performed rescue experiments functionally." (PMID 33448691, 2020). "Inhibited miR‐32‐5p or upregulated SOX4 could markedly counteract the inhibitory effects of silencing HNF1A‐AS1 on glioma malignant biological behaviors." (PMID 33448691, 2020). "From qRT‐PCR results, we found a significant elevation of SOX4 in four glioma cells." (PMID 33448691, 2020). "Moreover, TGF-beta induced expression of SOX2 was mediated by SOX4 in glioma-initiating cells." (PMID 24828201, 2014). "The five glioma subpopulations were as follows: C0 CHCHD2P9+ glioma cells (2,821 cells), C1 MALT1+ glioma cells (2,124 cells), C2 MT1G+ glioma cells (1,614 cells), C3 SOX4+ glioma cells (1,575 cells), and C4 ISG15+ glioma cells (128 cells)." (PMID 40630954, 2025). "SOX4 forms a complex of transcripts with OCT‐4 protein that triggers SOX2 expression and enhances the carcinogenicity of glioma cells." (PMID 36987665, 2023). "SOX4 is a key transcriptional target of the TGF-β signaling pathway in various cell types, including breast epithelial cells, glioma cells, and pancreatic cancers." (PMID 35151689, 2022). "In glioma, SOX2 expression promotes stemness via downstream activation of TGFβ signaling, which also promotes GSC stemness by activating SOX4." (PMID 34012965, 2021). "All in all, we initially found that MYC induced HNF1A‐AS1 overexpression promoted glioma progression via modulating miR‐32‐5p/SOX4 axis, providing potent reference value for targeting HNF1A‐AS1 in future therapeutic strategies of glioma." (PMID 33448691, 2020). "HOXD-AS1 modulates the miR-130a/E2F8 (E2F transcription factor 8) axis in glioma, the miR-130a-3p/SOX4 (SRY-box 4) axis in liver cancer, and the miR-608/FZD4 (frizzled class receptor 4) axis in ovarian cancer." (PMID 29702599, 2018). "In particular SOX4, a direct TGF-β target gene, was demonstrated to sustain tumorigenicity of glioma-initiating cells." (PMID 26188123, 2015). "Others and we have showed that SOX4 is a target of TGF-beta signaling and is involved in maintaining stemness of glioma-initiating cells." (PMID 25366337, 2014). "SOX4 has been demonstrated to be a downstream target of the TGF-β signaling pathway in a number of cell types including T-helper cells and glioma." (PMID 23301048, 2013). "In glioblastoma, SOX4 serves as a direct TGF-β target gene, conducts an alternative non-SMAD TGF-β signaling, and induces SOX2 expression to maintain the stemness of glioma-initiating cells." (PMID 23251334, 2012). "For example, H19 enhances Sox4 expression by sponging miR-130a-3p, which promotes EMT in glioma." (PMID 33028341, 2020). "Similarly, SOX4 and POU class 5 homeobox 1 (OCT-4) proteins were also shown to activate SOX2 transcription in glioma initiating cells." (PMID 23613880, 2013). "Furthermore, another study reported that sex-determining region Y-box 4/2 (SOX4/2), including SOX2 and SOX4, induced by the SMAD2/3 pathway, which is activated by TGFβ1 (mainly from M2 TAM), promotes the stemness and migration abilities of glioma cells." (PMID 37759870, 2023). "However, it was confirmed that SOX4 can also promote tumor progression by interacting with the transcription factors Smad2/3 as well as dephosphorylating PPM1A and FHL3, which decreases the self-renewal capacity of glioma stem cells." (PMID 35686099, 2022). "Last but not least, SOX4 overexpression could significantly reduce the biological effects induced by silencing HNF1A‐AS1 in glioma cells, which further confirmed the ceRNA role of SOX4." (PMID 33448691, 2020).